ADH1B (alcohol dehydrogenase 1B (class I), beta polypeptide)
Diseases named in the same sentence as ADH1B in open-access papers (continued):
Sharing a sentence is not in itself a finding about the gene and the disease.
Obesity (10 papers, 2015 to 2026). Accumulation of substantial excess body fat. "Unexpectedly, ADH1B in fasting adipose tissue emerged as the strongest causal candidate gene for obesity/insulin resistance (OB/IR)." (PMID 33479282, 2021). "In summary, these direct correlations of ADH1B expression with various metabolic measures indicate a strong association of ADH1B with obesity and insulin resistance and a possible link with prediabetes." (PMID 25830378, 2015). "In conclusion, we have established that there is a strong and consistent pattern of expression of human adipose ADH1B associated with various measures of obesity and IR." (PMID 25830378, 2015). "Together, all these findings showing the strong association of ADH1B gene and ADH1B expression with BMI and obesity-related traits indicates that ADH1B may be involved in the etiology of obesity, however details of that relationship remain to be uncovered." (PMID 33479282, 2021). "FAS and ADH1B mRNA expression levels (as it occurred with SWATH-MS analysis) decreased considerably during obesity and were restored after weight loss, even exceeding the values of the controls, although it was not statistically significant due to the reduced number of patients after BS." (PMID 31941045, 2020). "Our findings suggest that ADH1B is involved in the proper development and metabolic activity of adipose tissues and this function is suppressed by obesity." (PMID 33479282, 2021). "We previously showed that gene expression of alcohol dehydrogenase 1B (ADH1B) was inversely correlated with obesity and IR in subcutaneous adipose tissue of Mexican Americans." (PMID 33479282, 2021). "In the current study, we performed molecular studies, using human subcutaneous pre-adipocyte cell lines to examine the role of ADH1B protein in adipocytes and the potential involvement of ADH1B in the development of obesity." (PMID 33479282, 2021). "The data suggests obesity blunts ADH1B protein expression; however, it is possible that ADH1B expression is decreased due to a corresponding decrease in differentiation." (PMID 33479282, 2021). "The relationship of ADH1B expression, in adipose tissue and subcutaneous adipocytes, with BMI and insulin activity underscores the importance of its potential role in obesity and insulin resistance." (PMID 33479282, 2021). "We also observed that ADH1B protein and mRNA expression levels decreased with obesity, but BS restored and even exceeded the values of the control group, demonstrating a negative correlation with BMI, insulin sensitivity and adipocytes size." (PMID 31941045, 2020). "Winnier’s study provided strong experimental support for the potential roles for ADH1A and ADH1B in obesity, insulin resistance and T2D." (PMID 28496128, 2017). "Taken together these findings provide strong experimental support for a potential role for adipose ADH1B in obesity/IR and T2D." (PMID 25830378, 2015). "Similarly, we found a decrease in the expression of ADH1B, an enzyme crucial for adipose tissue development and metabolic activity, which is known to be suppressed in obesity." (PMID 41077621, 2026). "ADH1B affects the metabolic functions of adipose tissue, tumor progression, and metabolic diseases such as obesity, which means that it may serve as a potential treatment target for PTC patients." (PMID 40084144, 2025). "Despite the high and specific expression of ADH1B in adipose tissue, the functional role of ADH1B protein in adipose and its relationship to obesity is unknown." (PMID 33479282, 2021). "These preliminary findings point to an unsuspected potential role for ADH1B in adipocytes and the adipocyte response to insulin, which may be a factor in obesity and related metabolic disorders." (PMID 33479282, 2021). "The decreased expression of ADH1B in adipose tissue was related to obesity, systemic insulin resistance, and a decline in β cell function, which may be associated with prediabetes." (PMID 32337289, 2020).
Obesity (continued). "One possible mechanism of ADH1A and ADH1B in adipose tissue and obesity has been proposed to explain their negative association with obesity-related traits and insulin resistance." (PMID 28496128, 2017). "It is, therefore, possible that the link between decreased ADH1B gene expression and obesity/IR which we have established in this study may exist both in individuals who do not ultimately develop T2D and those who are highly likely to develop this disease." (PMID 25830378, 2015). "Thus, approved drug targeting ADH1B for age-related macular degeneration could be repurposed for treatment of obesity." (PMID 39406990, 2024). "However, this does not preclude a role for ADH1B in T2D given the fact that obesity and IR are primary risk factors for T2D." (PMID 25830378, 2015). "From a total of 682 studies with P values ≤ 10–4 only one SNP in a single study was significantly associated with ADH1B but the phenotype “upper aerodigestive tract cancers” was clearly not related to the obesity/IR phenotypic association discovered in the present study." (PMID 25830378, 2015). "Proteins involved in energy metabolism, such as AK2, ADH1B, ACADS, and GCDH, were downregulated in patients with obesity, suggesting impaired lipid metabolism and mitochondrial dysfunction." (PMID 41077621, 2026). "ADH1B also regulates FABP4 expression during subcutaneous adipocyte differentiation and is inversely correlated with obesity and insulin resistance." (PMID 39406990, 2024). "Except for these and alcohol dehydrogenase 1B (ADH1B), malic enzyme 1 (ME1) and ethylmalonyl-CoA decarboxylase (ECHDC1), other expressed genes in the cluster have little known information in the context of obesity and chronic diseases." (PMID 30380678, 2018). "This indicates that the significant inverse correlations between ADH1B expression and obesity/IR traits were not confounded by drinking status." (PMID 25830378, 2015). "Given that ADH1B knockdown reduces insulin‐stimulated glucose uptake, its dysregulation in our study may reflect impaired insulin sensitivity, which is consistent with the reduced insulin‐stimulated VAT glucose uptake in obesity in our previous report." (PMID 41077621, 2026). "It appears that the robust relationship observed between adipose tissue ADH1B gene expression with obesity/IR, at the RNA and protein level, may be present in both normal glucose tolerant and pre-diabetic individuals." (PMID 25830378, 2015).
Stroke (10 papers, 2012 to 2025). Sudden impairment of blood flow to a part of the brain due to occlusion or rupture of an artery to the brain. "We evaluated the association of stroke with genetic polymorphisms in the alcohol metabolizing genes, alcohol dehydrogenase 1B (ADH1B, rs1229984) and aldehyde dehydrogenase 2 (ALDH2, rs671) genes based on alcohol consumption." (PMID 34051793, 2021). "Other studies provided little evidence for an association between ADH1C genotype and coronary events or stroke across strata of alcohol consumption and the same applies to the association between ADH1B genotype and acute coronary syndrome." (PMID 22363810, 2012). "Regarding the relationship between alcohol exposure and stroke, an alcohol dehydrogenase genotype 1B (ADH1B, rs1229984), heterozygous or homozygous in drinks consumers, has been associated with an increased ICH risk." (PMID 37304967, 2023). "We examined the relationship among stroke, alcohol consumption, potential confounding factors, and SNPs rs1229984 and rs671 in two important alcohol metabolizing genes, ADH1B and ALDH2, respectively." (PMID 34051793, 2021). "We examined the relationship between genetic polymorphisms of ADH1B rs1229984, ALDH2 rs671, and stroke in relation to alcohol consumption among Taiwanese adults." (PMID 34051793, 2021). "We found less genetic evidence for an alcohol–stroke relationship than an early MR study that found that the ADH1B rs1229984 A-allele (associated with reduced alcohol consumption) was also associated with lower CHD and stroke risk." (PMID 33275596, 2020). "A one-sample MR study including 261,991 European descents showed that the ADH1B-rs1229984 variant is associated with non-drinking and lower alcohol consumption had a reduced risk of ischemic stroke (but not the combined subtypes of stroke) than those without the genetic variant." (PMID 39574800, 2024).
lung carcinoma (9 papers, 2017 to 2025). "Another two sample study on Asian population using ALDH2-rs671 and ADH1B-rs1229984, an increase of 280 g/week in alcohol consumption was associated with a decreased risk of lung cancer in men [HR = 0.81 (0.67–0.98)]." (PMID 39574800, 2024). "Some studies have shown that the decrease of ADH1B is associated with human lung cancer." (PMID 34970420, 2021). "Fibroblasts were a heterogeneous population, and a previous study revealed ADH1B + CAF mainly originated from the CCL19-expressing ADH1B+ cells specifically found in TLS25 in lung cancer." (PMID 37537219, 2023). "For lung cancer patients, high expression of ADH1B, ADH1C, ADH4, and ADH5 genes can achieve a better prognosis." (PMID 36212135, 2022). "At the same time, we also found that 11 of 17 (64.7%) tumors had decreased ADH1B mRNA (20.93-fold) or INMT mRNA (10.22-fold) in HIV lung cancer." (PMID 30177858, 2018). "Thus, we will further investigate the molecular mechanisms of TOP2A and ADH1B genes in lipid metabolism regulation and lung cancer progression in upcoming studies." (PMID 37985446, 2023). "On the other hand, SYNPO2, ADH1B and INMT were found to be repressed in HIV-associated lung cancer." (PMID 30177858, 2018). "Additionally, ADH1B, ZNF300, GPR161, and RDH11 were presented as the novel regulatory genes in lung injury and lung cancer." (PMID 39940682, 2025). "Glutathione S-Transferase Omega 1 (GSTO1), Sulfotransferase Family 2B Member 1 (SULT2B1), ADH1A, ADH1B, and ADH1C were downregulated in lung cancer versus normal tissue, while ALDH3A2 and MTHFD2 were upregulated in lung cancer tissue versus normal adjacent tissue." (PMID 31717324, 2019). "We also found decreased ADH1B, INMT and SYNPO2 mRNA levels in HIV lung cancer." (PMID 30177858, 2018). "However, it is not known whether TOP2A and ADH1B can also affect lipid metabolism in lung cancer patients with different subtypes." (PMID 37985446, 2023). "This combination of TOP2A and ADH1B gene diagnostics and clinical lipid panel investigations might be an effective intervention for early and accurate diagnosis, targeted therapy, and improved prognosis of LUAD, thus enhancing the current clinical management strategies of lung cancer." (PMID 37985446, 2023).
gout (8 papers, 2017 to 2025). A condition characterized by painful swelling of the joints, which is caused by deposition of urate crystals. "Alcohol consumption is a well-known risk factor for gout, and ADH1B plays a critical role in modulating this risk." (PMID 41075270, 2025). "In summary, this study has identified novel interactions with alcohol consumption at ADH1B and MLXIPL for association with serum urate level and at ADH1B for association with hyperuricaemia and gout among individuals of European ethnicity." (PMID 38331848, 2024). "Beer intake had the most significant interaction with ADH1B for association with serum urate and gout among men, while wine intake had the most significant interaction among women." (PMID 38331848, 2024). "We observed significant interactions with alcohol consumption at rs1229984 in the ADH1B locus and rs6460047 in the MLXIPL locus for association with serum urate level, and at ADH1B rs1229984 only for association with hyperuricaemia and gout." (PMID 38331848, 2024). "Only ADH1B rs1229984 demonstrated significant interaction with continuous alcohol intake for association with gout among all participants (P = 8.2 × 10−9)." (PMID 38331848, 2024). "This study determined three proteins causally associated with gout by Mendelian randomization (MR) analysis: ADH1B, BMP1 and HIST1H3A." (PMID 38831441, 2024). "Between the individual alcoholic beverage types, beer intake demonstrated the most significant interaction with ADH1B rs1229984 for association with gout among men, while wine intake had the most significant interaction among women." (PMID 38331848, 2024). "The fast-metabolising variant of ADH1B rs1229984 is associated with increased serum urate and gout among Japanese male consumers of alcohol." (PMID 38331848, 2024). "Through a Mendelian randomization (MR) analysis, we identified three proteins causally associated with gout: ADH1B, BMP1, and HIST1H3A." (PMID 38831441, 2024). "The lead SNP at GCKR, rs1260326, has been shown to be a risk variant for gout in a separate GWAS, and rs1229984 in ADH1B has been identified for systolic blood pressure using a functional enrichment approach." (PMID 31998841, 2020). "Next, we investigated the combined effects on gout of the common variants of ADH1B (rs1229984) and ALDH2 (rs671)." (PMID 28566767, 2017). "We therefore performed an association analysis between gout and a common dysfunctional variant of ADH1B, rs1229984 (His48Arg)." (PMID 28566767, 2017). "Because the sample size of non-drinkers was relatively small, further studies are necessary to clarify the effects of alcohol consumption on the association between gout and common variants of ADH1B and ALDH2." (PMID 28566767, 2017). "rs1229984 of ADH1B showed a significant association with gout, even after adjustment for alcohol consumption (P = 6.1 × 10−3; OR = 1.83; 95% CI: 1.19–2.81)." (PMID 28566767, 2017). "In this study, for the first time, we revealed a significant association between a common dysfunctional variant of ADH1B (rs1229984) and gout." (PMID 28566767, 2017). "On the other hand, although the association between gout and rs1229984 of ADH1B was still significant even after adjustment for alcohol consumption and in drinkers, this association was not significant in non-drinkers." (PMID 28566767, 2017). "Between the individual alcoholic beverage types, beer intake was observed to have the most significant interaction with ADH1B rs1229984 for association with serum urate level, hyperuricaemia, and gout and with MLXIPL rs6460047 for association with serum urate level among all participants." (PMID 38331848, 2024). "The association of ADH1B with serum urate and gout may occur through the modulation of alcohol metabolism rate among consumers of alcohol." (PMID 38331848, 2024). "This suggests that the association of ADH1B with serum urate level and gout may occur through the modulation of alcohol metabolism rate rather than downstream effects on alcohol intake behaviour." (PMID 38331848, 2024).
gout (continued). "Recent GWAS identified genetic variants in urate transporters (ABCG2, SLC2A9, SLC22A11) and metabolic genes (GCKR, ADH1B) to be associated with the transition from hyperuricaemia to gout, and several of these associated with serum urate (SU) and gout in previous studies." (PMID 35633389, 2022). "In addition, a missense SNP of ADH1B gene rs1229984 (H48R) was also associated with gout in a Japanese population." (PMID 30123371, 2018). "Thus, we initially assumed that the associations between gout and common variants of ADH1B and ALDH2 would be accounted for by alcohol consumption." (PMID 28566767, 2017). "Therefore, from the point of view of alcohol consumption, further studies are necessary to be able to elucidate the association between gout and common variants of ADH1B and ALDH2." (PMID 28566767, 2017). "However, the association between gout and common variants of ADH1B has hitherto remained unreported, prompting us to investigate the association between gout and common dysfunctional variants of ADH1B (rs1229984) and ALDH2 (rs671)." (PMID 28566767, 2017). "Among the other genes significantly associated with gout, seven loci have also been previously identified in GWAS, including those in the genes SLC17A1, GCKR, SLC22A11, ADH1B, MLXIPL, RREB1 and SLC16A9." (PMID 41075270, 2025). "In this large study of European participants, novel interactions with alcohol consumption were identified at ADH1B and MLXIPL for association with serum urate level and at ADH1B for association with hyperuricaemia and gout." (PMID 38331848, 2024). "However, other studies observed that the association of ADH1B with hyperuricaemia and gout remained significant after adjusting for alcohol consumption, suggesting that ADH1B may also associate with serum urate and gout among alcohol consumers through other pathways." (PMID 38331848, 2024). "ADH1B also demonstrated interaction with alcohol consumption for hyperuricaemia (P = 7.9 × 10−13) and gout (P = 8.2 × 10−9)." (PMID 38331848, 2024). "In summary, our data show that common variants of ADH1B (rs1229984) and ALDH2 (rs671) are independently associated with gout, which indicates that the genotyping of rs1229984 and rs671 can be useful for the evaluation of gout risk." (PMID 28566767, 2017). "We performed genotyping of rs1229984 (His48Arg) of ADH1B using 1,048 clinically defined gout cases and 1,334 controls of Japanese male." (PMID 28566767, 2017). "Non-additive effects with alcohol intake were also observed at ADH1B rs1229984 for gout." (PMID 38331848, 2024). "ADH1B (OR = 0.15, 95% CI = 0.07–0.35), BMP1 (OR = 7.04, 95% CI = 3.35–14.78), and HIST1H3A (OR = 205.85,95%CI = 78.35–540.8) were found to be significantly associated with gout at the Bonferroni-corrected threshold (P 1.719 10 − 6)." (PMID 38831441, 2024). "ADH1B and GCKR were associated with gout, and ADH1B alone with hypertension." (PMID 31998841, 2020). "Contrary to this expectation, these associations were still significant even after adjustment for alcohol consumption, which indicates that common variants of ADH1B and ALDH2 can be associated with gout susceptibility through not only alcohol consumption but also other factors and/or mechanisms." (PMID 28566767, 2017). "On the other hand, to our knowledge, the association between gout and common variants of ADH1B has not hitherto been reported." (PMID 28566767, 2017). "In the genotype-stratified association analyses, ADH1B and MLXIPL were associated with serum urate level and ADH1B was associated with hyperuricaemia and gout among consumers of alcohol but not non-consumers." (PMID 38331848, 2024). "While no other identified genes were currently linked to approved gout medications, the associated drugs targeting genes such as ABCG2, SLC22A11, and ADH1B—involved in metabolic and inflammatory pathways—may hold potential for repurposing in gout treatment." (PMID 41075270, 2025).
hepatocellular carcinoma (8 papers, 2016 to 2025). A malignant tumor that arises from hepatocytes. "Alcohol dehydrogenase, ADH1C and ADH1B, are members of the alcohol dehydrogenase family and are associated with many cancers, especially hepatocellular carcinomas." (PMID 41374967, 2025). "A large cohort analysis stated that the alteration of ADH1B increases the risk of hepatocellular carcinoma." (PMID 37540213, 2023). "Additionally, ADH1B expression is notably reduced in hepatocellular carcinoma (HCC), with low expression levels associated with poor prognosis." (PMID 40296873, 2025). "Liu J reported that ADH1B and ALDH2 SNPs were significantly associated with pathogenesis of hepatocellular carcinoma medicated through alcohol drinking." (PMID 27927211, 2016).